LRIG1 (leucine rich repeats and immunoglobulin like domains 1)
Diseases named in the same sentence as LRIG1 in open-access papers (continued):
Sharing a sentence is not in itself a finding about the gene and the disease.
cutaneous squamous cell carcinoma (4 papers, 2018 to 2021). "Our work on β-HPV-induced cutaneous squamous cell carcinomas identified a novel Lrig1+ hair follicle junctional zone keratinocyte stem cell population as the basis for field cancerisation." (PMID 29632522, 2018).
lung cancer (4 papers, 2015 to 2024). A malignant neoplasm involving the lung. "Decreased LRIG1 expression has been associated with poor prognosis in a range of epithelial tumours, including lung cancer." (PMID 34385275, 2022). "Loss of heterozygosity of LRIG1 is seen in 75% of human lung cancer cell lines and low levels of LRIG1 expression have been correlated with decreased overall survival in patients with NSCLC." (PMID 34385275, 2022). "Together, our findings identify LRIG1 as a marker of basal airway progenitor cells with high proliferative potential and as a regulator of pre-invasive lung cancer progression." (PMID 34385275, 2022). "Currently, a limited number of studies have investigated the roles of LRIG1 in lung cancer." (PMID 26632716, 2015). "LRIG1 (leucine-rich repeats and immunoglobulin-like domains 1) is downregulated in pre-invasive airway lesions and invasive LUSC tumours and this correlates with decreased lung cancer patient survival." (PMID 34385275, 2022).
non-small cell lung carcinoma (4 papers, 2015 to 2019). A group of at least three distinct histological types of lung cancer, including non-small cell squamous cell carcinoma, adenocarcinoma, and large cell carcinoma. "Subsequent genomic, histological and functional studies have demonstrated downregulation and tumor-inhibitory effects of LRIG1, and correlated LRIG1 to favorable clinical outcomes, in several human cancers including breast, bladder, colon, cervical, and non-small-cell lung cancers and gliomas." (PMID 31792211, 2019).
acute myeloid leukemia (3 papers, 2021 to 2024). Acute myeloid leukemia (AML) is a group of neoplasms arising from precursor cells committed to the myeloid cell-line differentiation. "MAGI2-AS3 was determined to be downregulated in leukemic stem cells and inhibited cell renewal by upregulating LRIG1, thereby improving the deterioration of acute myeloid leukemia." (PMID 38907263, 2024). "In acute myeloid leukemia, lncRNA MAGI2-AS3 recruits TET2 to LRIG1 promoter, inducing up-regulation of LRIG1 and inhibition of leukemic stem cell self-renewal." (PMID 35292092, 2022).
basal cell carcinoma (3 papers, 2019 to 2025). A carcinoma involving the basal cells. "A nuclear LRIG1 staining pattern has been observed in several cancer types, for example, in basal cell carcinoma, non‐small‐cell lung cancer, and head and neck cancer." (PMID 40702701, 2025). "Basal cell carcinoma has also been shown to express the epithelial stem cell markers CK19, LGR5, LRIG1, and SOX9." (PMID 34331569, 2021).
colorectal tumor (3 papers, 2013 to 2021). "In addition to its expression in normal gastrointestinal tissues, Lrig1 is expressed at low levels in several types of cancer and is overexpressed in both prostate and colorectal tumors." (PMID 23372710, 2013). "The data revealed that the expression of LRIG1 in both mRNA and protein levels was down regulated in colorectal tumor tissues (P < 0.01) but is not clinically relevant prognostic indicator in CRC." (PMID 33461538, 2021).
esophageal cancer (3 papers, 2015 to 2024). A primary or metastatic malignant neoplasm involving the esophagus. "A GEO-based prognostic model consisting of six gene products (ARHGAP11A, H1.4, HMGB3, LRIG1, PRR11, and COL4A1) has been shown to be a reliable predictor of esophageal cancer." (PMID 39062899, 2024). "A prognostic model consisting of six gene products (HMGB3, ARHGAP11A, H1.4, LRIG1, PRR11, and COL4A1) is a reliable predictor of esophageal cancer." (PMID 39062899, 2024).
hepatocellular carcinoma (3 papers, 2018 to 2022). A malignant tumor that arises from hepatocytes. "A correlation between lower LRIG1 expression and increased tumour size has been identified in hepatocellular carcinoma." (PMID 34385275, 2022). "LRIG1 is a known tumor suppressor and has been shown to be a positive prognostic marker in other malignancies such as hepatocellular carcinoma." (PMID 34331569, 2021).
leukemia (3 papers, 2012 to 2021). A malignant (clonal) hematologic disorder, involving hematopoietic stem cells and characterized by the presence of primitive or atypical myeloid or lymphoid cells in the bone marrow and the blood. "Moreover, it has been reported that LRIG1 expression is downregulated in leukemia." (PMID 33893245, 2021).
oropharyngeal cancer (3 papers, 2017 to 2021). Carcinoma, predominantly squamous cell, arising from the epithelial cells of the oropharynx. "In both PVC and oropharyngeal cancer, a high expression of LRIG1 was identified and LRIG1 expression was revealed as an independent, positive prognostic factor." (PMID 28841699, 2017).
renal cell carcinoma (3 papers, 2003 to 2014). "Previous studies have revealed altered expression of epidermal growth factor (EGF) receptor (EGFR)-family members and their endogenous inhibitor leucine-rich and immunoglobulin-like domains 1 (LRIG1) in renal cell carcinoma (RCC)." (PMID 22554477, 2012). "Previous studies have revealed altered expression of epidermal growth factor receptor (EGFR)-family members and their endogenous inhibitor leucine-rich and immunoglobulin-like domains 1 (LRIG1) in renal cell carcinoma (RCC)." (PMID 22554477, 2012). "In all, 31 renal cell carcinomas (RCCs) were examined for expression of the potential tumour suppressor LRIG1 (formerly Lig-1) and the epidermal growth factor receptor (EGFR)." (PMID 14520461, 2003).
sebaceous gland tumours (3 papers, 2015 to 2022). "Importantly, development of sebaceous tumors is associated with an increase in LRIG1+ stem cells indicating either a sequential cellular process of tumor initiation or formation of sebaceous tumors by different hair follicle stem cell pools." (PMID 36439142, 2022). "However, this correlation between Lrig1 expression and differentiation was not seen in SC-driven aggressive sebaceous tumours indicating that Lrig1 expression is differently regulated in different types of tumours." (PMID 25608467, 2015).
squamous cell carcinoma of the skin (3 papers, 2012 to 2017). "In a study of squamous cell carcinoma of the skin, LRIG1 showed the highest expression in well-differentiated tumours, and these patients also proved to have the best survival." (PMID 28841699, 2017).
acne (2 papers, 2020 to 2026). An inflammatory process of the sebaceous glands which is characterized by comedones, nodules, papules and/or pustules on the skin. "Wnt signaling regulates the proliferation and specification of junctional LRIG1+ cells, resulting in acne pathogenesis." (PMID 32765835, 2020). "Alternative treatments are suggested by the "comedo switch" hypothesis, which attributes acne to aberrant differentiation of LRIG1+ sebaceous progenitor cells." (PMID 41897366, 2026).
atherosclerosis (2 papers, 2016 to 2017). A disease characterized by the build-up of fatty material and calcium deposition in the arterial wall resulting in partial or complete occlusion of the arterial lumen.
atrial fibrillation (2 papers, 2022 to 2023). A disorder characterized by an electrocardiographic finding of a supraventricular arrhythmia characterized by the replacement of consistent P waves by rapid oscillations or fibrillatory waves that vary in size, shape and timing and are accompanied by an irregular ventricular response. "We also replicate a previously reported finding showing that LRIG1 (leucine-rich repeats and immunoglobulin-like domains 1) lies on the causal path for atrial fibrillation, T2D and self-reported hypercholesterolemia." (PMID 36349687, 2023). "LRIG1 encodes for a transmembrane protein, with its variants associated with carotid intima media thickness and atrial fibrillation." (PMID 35886906, 2022).
colon adenoma (2 papers, 2020 to 2021). An adenoma that arises from the colon. "The Lrig1-CreERT2/+;Apcfl/+ inducible mouse model of colonic adenoma is based on the conditional Cre-recombinase-driven loss of a single copy of Apc under the control of the Lrig1 promoter." (PMID 32059662, 2020). "This work sought to understand the genomic changes occurring during the early stages of tumorigenesis in rapidly-growing colonic adenomas in Lrig1-CreERT2/+;Apcfl/+ mice." (PMID 32059662, 2020). "The proposed mechanism of colonic adenoma formation in the Lrig1-CreERT2/+;Apcfl/+ model is the following: Transcriptional silencing of Apc leads to a decrease in goblet cells and a corresponding increase in inflammatory reactive oxygen species (ROS) in the distal colon." (PMID 32059662, 2020).
gastric cancer (2 papers, 2018 to 2020). A primary or metastatic malignant neoplasm involving the stomach. "It has been reported that miR-20a/LRIG1 axis might regulate gastric cancer drug resistance through EGFR-mediated PI3K/AKT and MAPK/ERK signaling." (PMID 30497428, 2018).
intestinal tumor (2 papers, 2013 to 2018). "Since the discovery of specific ISC populations, including Lgr5+, Bmi1+, or Lrig1+ ISCs, and their ability to serve as the origin of intestinal tumor development, much interest has been focused on their function in the context of diet and aging." (PMID 29904634, 2018).
malignant glioma (2 papers, 2018 to 2019). A grade III or grade IV glioma arising from the central nervous system. "As for LRIG1, A recent knockout mouse study showed that Lrig1 is a haploinsufficient tumor suppressor gene in malignant glioma." (PMID 31358815, 2019).
Obesity (2 papers, 2021 to 2022). Accumulation of substantial excess body fat. "Genetic variants in LRGI1 have been previously shown to be linked to birth weight, blood pressure and cardiovascular endpoints, while methylation of CpG sites in LRIG1 has been linked to obesity in children, as well as birthweight and maternal adiposity." (PMID 35393509, 2022).
papilloma (2 papers, 2019 to 2021). A benign epithelial neoplasm that projects above the surrounding epithelial surface and consists of villous or arborescent outgrowths of fibrovascular stroma. "The first papillomas arose 5 weeks after tumor initiation in LRIG1‐TG mice and after 6 weeks in controls." (PMID 33786987, 2021). "cSCC is usually characterized by high KRT6 expression levels, and KRT6 was detected in the IFE of DMBA/TPA‐treated skin in both groups but was decreased in papillomas of LRIG1‐TG mice." (PMID 33786987, 2021). "Our results show high expression of MLANA in papillomas as well as in the epidermis and the dermis of LRIG1‐TG animals and only low expression in control skin." (PMID 33786987, 2021). "However, while 100% of LRIG1‐TG mice developed papillomas, only 86% of control animals were affected." (PMID 33786987, 2021). "Interestingly, it has recently been shown that in HPV8 transgenic mice papilloma formation is driven by Lrig1+ hair follicular stem cells which expand into the infundibulum and overlaying epidermis." (PMID 30875834, 2019). "However, KRT6 expression was reduced in LRIG1‐TG papillomas." (PMID 33786987, 2021). "Compared to control mice, LRIG1‐TG mice showed no alteration during chemically induced skin carcinogenesis, but displayed a decreased proliferation rate of papillomas." (PMID 33786987, 2021). "Both papillomas and IFE of LRIG1‐TG mice showed a significantly decreased proliferation rate." (PMID 33786987, 2021). "H&E staining of papillomas from LRIG1‐TG and control mice showed no morphological differences." (PMID 33786987, 2021).
skin cancer (2 papers, 2021 to 2022). "K14-HPV8-CER transgenic mice express the complete early genome region of human papillomavirus type 8 (HPV8) and develop skin tumours attributed to the expansion of the Lrig1+ stem cell population." (PMID 35406439, 2022). "We showed that HPV8 differentially regulates 397 cellular genes in skin tumours and subverts the expression pattern of 23 genes in Lrig1+ cells." (PMID 35406439, 2022). "LRIG1 expression was significantly increased in three of four human skin cancer cell lines compared to HaCaT keratinocytes: A431, A375, and SK‐MEL28." (PMID 33786987, 2021). "As LRIG1 is a marker for epidermal progenitor cells, its expression was very low and barely detectable in the HaCaT cell line but was significantly upregulated in three of the four skin cancer cell lines." (PMID 33786987, 2021). "To further understand the oncogenic pathways underlying skin tumour formation we examined the gene expression network in skin tumours of K14-HPV8-CER mice and compared the differentially expressed genes (DEG) with those of the Lrig1-EGFP-ires-CreERT2 mice." (PMID 35406439, 2022). "To understand the role of HPV8 gene expression in Lrig1+ keratinocytes, we determined the transcriptional network in K14-HPV8-CER skin tumours and compared it to the already known pattern in Lrig1 stem cells." (PMID 35406439, 2022).
type 2 diabetes (2 papers, 2021 to 2023). "Human LRIG1 variants were strongly associated with increased body mass index (BMI) yet protected against type 2 diabetes; these effects were likely mediated by altered adipocyte morphology." (PMID 33469151, 2021). "They find that mutant LRIG/sma-10 variant worms exhibit lipid storage defects and that human LRIG1 variants are associated with higher body mass index, yet protect against type 2 diabetes." (PMID 33469151, 2021). "We further examined whether genetic variation in LRIG1 was associated with risk of type 2 diabetes, BMI, and adipocyte morphology among humans." (PMID 33469151, 2021). "Importantly, specific human LRIG1 gene variants were associated with a decreased risk of type 2 diabetes, increased BMI, and altered adipocyte morphology, suggesting that LRIG proteins play important physiological roles in the regulation of lipid homeostasis in humans." (PMID 33469151, 2021). "Because the functional importance of Lrig1 in various metabolic diseases such as type 2 diabetes has been explored very recently, it remains to be seen what therapeutic efficacy of Lrig1 mAb stimulating Treg cell functions would show to the patient with type 2 diabetes." (PMID 37666819, 2023). "Nevertheless, LRIG1, LRIG3, or other functionally associated proteins may provide novel targets for the prevention or treatment of type 2 diabetes or other metabolic diseases." (PMID 33469151, 2021).
vaginal cancer (2 papers, 2017 to 2024). A primary or metastatic malignant neoplasm involving the vagina. "LRIG1 is generally considered a positive prognostic factor, as seen in vaginal carcinoma, prostate, breast, lung, and uterine cervical cancer, among others." (PMID 38918827, 2024). "However, whether cervical and vaginal cancers depend on growth factor signalling for their growth, and whether LRIG1 can inhibit this growth, remain to be determined." (PMID 28841699, 2017).
astrocytomas (1 paper, 2025). "This is in line with Ye and colleagues’ findings, who showed downregulated LRIG1 expression in astrocytoma compared to surrounding control tissue." (PMID 41201961, 2025). "For example, a previous study showed reduced expression of LRIG1 in astrocytomas compared to surrounding control tissue." (PMID 41201961, 2025).
autoimmune disease (1 paper, 2023). A disorder resulting from loss of function or tissue destruction of an organ or multiple organs, arising from humoral or cellular immune responses of the individual to their own tissue constituents. "Our study is the first report about the immunological functions of Lrig1 and its therapeutic potential for autoimmune disease using mAb therapy and autologous adoptive Treg cell therapy." (PMID 37666819, 2023). "When the Treg cell-stimulating mAb specific to Lrig1 is administered to patients with autoimmune disease, there is a possibility that the antibody binds to LRIG1+ cells, such as epithelial or intestinal stem cells in other tissues and may affect the proliferation status of the cells." (PMID 37666819, 2023).
Autoimmunity (1 paper, 2023). The occurrence of an immune reaction against the organism's own cells or tissues. "In conclusion, Lrig1 is an important regulator of suppressive T cell function and an exploitable target for treating autoimmune conditions." (PMID 37666819, 2023). "Therefore, targeting Lrig1 with mAb enhances the anti-inflammatory functions of the suppressive T cell population to protect autoimmunity in the EAE animal models." (PMID 37666819, 2023). "Therefore, the reagents targeting Lrig1 protein on the surface of the immuno-suppressive T cell population may provide a new therapeutic regime for treating autoimmunity." (PMID 37666819, 2023).
cataract (1 paper, 2019). Partial or complete opacity of the crystalline lens of one or both eyes that decreases visual acuity and eventually results in blindness. "In CC54, 5 genes (ANAPC1, RPIA, IGF2BP2, CYP2J2 and LRIG1) and 1 disease (Cataract) were extracted as a correlated set." (PMID 31345171, 2019).
chronic bronchitis (1 paper, 2021). A type of chronic obstructive pulmonary disease characterized by chronic inflammation in the bronchial tree that results in edema, mucus production, obstruction, and reduced airflow to and from the lung alveoli. "The expression correlation between AHR, LRIG1, and EGFR was examined in normal, emphysema, and chronically inflamed lung tissues (emphysema and chronic bronchitis are typical symptoms of COPD)." (PMID 34576152, 2021). "Strong LRIG1 reactivity was detected in lung tissues of emphysema and chronic bronchitis, rather than in normal lung tissue." (PMID 34576152, 2021).
chronic obstructive pulmonary disease (1 paper, 2021). A chronic and progressive lung disorder characterized by the loss of elasticity of the bronchial tree and the air sacs, destruction of the air sacs wall, thickening of the bronchial wall, and mucous accumulation in the bronchial tree. "We also affirmed low AHR but high LRIG1 levels in lung tissues of chronic obstructive pulmonary disease (COPD) patients." (PMID 34576152, 2021).
colitis (1 paper, 2023). Inflammation of the colon. "Adoptive transfer of CD4+Lrig1+ T cells alleviates autoimmune symptoms in colitis and lupus nephritis mouse models." (PMID 37666819, 2023).
dementia (1 paper, 2022). Loss of intellectual abilities interfering with an individual's social and occupational functions. "Here, LRIG1 was found to be significantly upregulated in symptomatic AD vs. non-symptomatic AD patients, suggesting that neurogenic outcome in these individuals could offset the clinical manifestation of dementia." (PMID 35681503, 2022).
dermatofibromas (1 paper, 2016). "Oncogenic β-catenin expression in LGR5+ cells led to formation of pilomatricomas, while LRIG1+ cells formed trichoadenomas and LGR6+ cells formed dermatofibromas." (PMID 26771241, 2016). "LGR5+ cells gave rise to pilomatricomas, while LRIG1+ cells formed trichoadenomas and LGR6+ cells formed infundibular cysts in the HF junctional zone and dermatofibromas in the IFE." (PMID 26771241, 2016).